NOTCH1 (notch receptor 1)
Diseases named in the same sentence as NOTCH1 in open-access papers (continued):
Sharing a sentence is not in itself a finding about the gene and the disease.
breast cancer (continued). "Analysis of 507 ER-negative and 1,356 ER-positive breast cancer patients revealed that keratin-5 associated with ER-negative breast cancers in seven out of 13 datasets, and that Notch-1 associated with ER-negative breast cancers in nine out of 16 datasets." (PMID 19025652, 2008). "Activating mutations of Notch1 drive oncogenesis in T-cell acute lymphoblastic leukemia through upregulation of Myc and NF-κB, while in breast cancer, nonsmall-cell lung cancer, and gliomas, Notch receptors promote proliferation, apoptosis resistance, and cancer stem cell maintenance." (PMID 41373772, 2025). "Similarly, the activation of the Jag1/Notch1 pathway has been implicated as a key factor in the drug resistance of trastuzumab in breast cancer." (PMID 41315239, 2025). "Furthermore, there was an association of NOTCH1 with basal type of breast cancer (OR = 2.53, 95% CI 1.18–5.43, p = 0.009)." (PMID 39153127, 2025). "Similarly, strong gain-of-function mutations in NOTCH1 have been found in several solid tumors, including breast cancer and adenoid cystic carcinoma." (PMID 38043798, 2024). "However, due to the number and complexity of NOTCH1 variants across breast cancer compared to traditional hotspot variants, classification of NOTCH1 variants remains understudied." (PMID 35186194, 2022). "For instance, cross-linked function of Notch and EGFR (epidermal growth factor receptor) signaling is highly associated with occurrence of breast cancer which was reported when Notch1 overexpression promoted cell growth accompanied by upregulated EGFR expression levels." (PMID 36017236, 2022). "Although previously thought to target mostly ion channel proteins rather than signalling pathways, NEDD4L (also known as NEDD4-2) has been linked to NOTCH1 down regulation in breast cancer cell lines, and high NEDD4L expression is associated with longer breast cancer relapse-free periods." (PMID 35204725, 2022). "Studies demonstrated that paeoniflorin inhibits the proliferation and invasion of breast cancer cells by suppressing the signaling pathway for the gene encoding the Notch-1 single-pass trans-membrane receptor and inhibits the macrophage-dependent metastasis of lung cancer." (PMID 36501418, 2022). "Other studies also show NOTCH1 activation and its association with metastatic breast cancer cells." (PMID 35846378, 2022). "Besides mutations in Notch1 and Notch2, approximately 50% of all human breast cancers show loss of Numb signaling, due to ubiquitination and degradation of Numb, which act as a tumor suppressor." (PMID 34572582, 2021). "Furthermore, increase of Notch1 activity marker was associated with worse clinical outcome in tamoxifen treated breast cancer patients, according to a meta-analysis of 458 women patients." (PMID 33324567, 2020). "Notch 1 is associated with HER2+ breast cancer resistance to trastuzumab (Section 4.1)." (PMID 32575680, 2020). "Inclusively, Notch1 and Notch3 oncogenic activity has been demonstrated in the mouse mammary gland and, in humans, high levels of Jagged1 and Notch1 proteins have been associated with particularly aggressive breast cancer cases." (PMID 33198378, 2020). "Moreover, meta-analysis of breast cancer studies revealed a significant association between high Notch1 expression and TNBC progression." (PMID 31105691, 2019). "In addition, more and more evidences have shown that Notch1 overexpression is strongly associated with breast cancer invasion, which is an important factor in maintaining the malignant phenotype of breast cancer stem cells." (PMID 30899449, 2019).
breast cancer (continued). "Additionally, the expression of functional CD147 and MMP-2 was significantly decreased in Notch1-deficient breast cancer cells which displayed impaired migration and invasion." (PMID 26675551, 2016). "Moreover, increased expression of Notch1 intracellular domain (Notch1-IC) is associated with poor survival in patients with breast cancer and other tumors." (PMID 27689990, 2016). "Whereas activating mutations in NOTCH1 have been identified in T-cell acute lymphoblastic leukemia and breast cancer, a tumor suppressor role for NOTCH signaling has been suggested in tumor types such as chronic myelomonocytic leukemia (CMML), HNSCC and lung SCC." (PMID 26759717, 2016). "The association of Notch1 expression with breast cancer molecular subtype was also analyzed." (PMID 26121683, 2015). "Although there is abundant evidence demonstrating that the Notch signaling pathway is closely associated with human breast cancer development, our study has provided novel insights into the role of Notch1 signaling in regulating EMT and invasion mainly in a Slug-dependent manner." (PMID 25645291, 2015). "Furthermore, the high expression levels of Notch1 and its ligand, Jagged-1, have been associated with a poor prognosis in breast cancer, bladder cancer, leukemia, intrahepatic cholangiocarcinoma and prostate cancer." (PMID 24932308, 2014). "Overexpression of Notch1 has been associated with breast cancer." (PMID 24970818, 2014). "Elevated Notch-1 in human breast cancer is associated with poor clinical outcomes." (PMID 24914410, 2014). "Unlike Notch pathway activation in T-cell acute lymphoblastic leukemia (T-ALL), which is mostly caused by Notch1 gene mutations, the induction of Notch signaling in breast cancer (and other carcinomas) is predominantly associated with ligand-dependent mechanisms of activation." (PMID 25309874, 2014). "Moreover, high-level expression of Notch-1 and its ligand Jagged-1 is associated with poor prognosis in breast cancer, bladder cancer, leukemia, and prostate cancer." (PMID 23688168, 2013). "Importantly, depletion of Notch-1 by siRNA together with As2O3 treatment caused cell growth inhibition and apoptosis to a greater degree in breast cancer." (PMID 22949821, 2012). "A Notch-1–survivin functional gene signature is a hallmark of basal breast cancer, and may contribute to disease pathogenesis." (PMID 19025652, 2008). "Furthermore, TGFβ increases Jagged 1 expression in metastatic breast cancer cells, and Jagged 1 activates NOTCH1 in osteoblasts, causing IL-6 expression to support the survival of metastatic breast cancer cells and leading to the development of osteoclasts mediating bone breakdown." (PMID 36517618, 2022). "Importantly, we demonstrated concomitantly high expression of Zeb1 and NICD in breast cancer patients with poorly differentiated high-grade tumors, highlighting that dysregulated Notch1-Zeb1 signaling is functionally linked to tumor stem cell traits in breast cancer." (PMID 33046710, 2020). "Moreover, Kaplan-Meier survival analysis revealed that high NUMB expression was associated with decreased distant disease-free survival (DDFS p = 0.0138) of breast cancer patients (left), while high Notch1 expression was associated with increased DDFS (p = 0.0035) of breast cancer patients (middle)." (PMID 27506933, 2016). "Notch1 mutations lead to oncogene expression in certain T cell acute lymphoblastic leukemias and a subset of breast carcinomas; deregulated Notch activity might also affect cell transformation, regulation of the cell cycle, progenitor/stem cell maintenance and the outcome of breast cancer." (PMID 23826634, 2013). "In this work, we excluded the involvement of Notch1 in SNO-induced breast cancer cellular dormancy by immunofluorescence/immunohistochemistry and molecular approaches, using breast cancer tissues and cell lines." (PMID 42135276, 2026).
breast cancer (continued). "For example, in breast cancer models, quercetin decreases Notch1 protein levels, arrests cell cycle progression, and increases apoptosis." (PMID 41602823, 2026). "In breast cancer, the overexpression of NOTCH1 and NOTCH4 in tumors suggests their role as oncogenes." (PMID 41561443, 2026). "Regarding the relationship between Notch signalling and breast cancer treatment, we observed a three-times higher benefit from chemotherapy for patients with low NOTCH1 mRNA expression in the tumour tissue." (PMID 39153127, 2025). "For instance, studies have shown that miR-200 family members can inhibit Notch1 expression by targeting its mRNA, thereby reducing the invasiveness of breast cancer cells." (PMID 40621472, 2025). "Our first aim was to assess the relationship between NOTCH1 mRNA expression levels and histopathological features of breast cancer tumours, as well as clinical characteristics of the correspondent early breast cancer (eBC) patients." (PMID 39153127, 2025). "DLK1’s different expression levels have been shown to inversely modulate the oncogenic potential of breast cancer cells through inhibition of NOTCH1 signaling." (PMID 41139924, 2025). "Silencing Notch1 or Notch4 inhibited the ability of breast cancer cells to self-renew and form tumor spheres." (PMID 41373772, 2025). "For example, miR-34a directly targets Notch1 mRNA, suppressing its expression and inhibiting breast cancer stem cell self-renewal." (PMID 40621472, 2025). "In breast cancer, Notch1 enhances cancer cell proliferation and sustains cancer stem cell activity, whereas Notch3 suppresses epithelial-mesenchymal transition (EMT) by activating glycogen synthase kinase 3 beta (GSK3β) expression." (PMID 41050674, 2025). "Consistent with this, we observe that SGK3 depletion elevates NOTCH1 levels in breast cancer cells, including the triple negative CAL-51 line, as it does in MCF10A cells." (PMID 39663000, 2025). "For instance, miR-338-5p was found to be able to affect the proliferation and metastasis of breast cancer by acting on the transcription factor ETS1 of Notch1, and this has been demonstrated in breast cancer tissues as well as xenograft tumor models." (PMID 40486870, 2025). "Cancer-associated fibroblasts (CAFs) have been shown to enhance the stem-like properties of breast cancer cells via the CCL2/NOTCH1 signaling pathway." (PMID 40485724, 2025). "The expression of MRPL52 is upregulated in breast cancer, particularly in hypoxic breast cancer cells, which regulates the ROS/Notch1/Snail signaling pathway to promote EMT, migration, and invasion, which enhances apoptotic resistance and metastatic potential." (PMID 40371222, 2025). "In breast cancer, Notch 1 and Notch 4 promote CSC self-renewal and the formation of metastatic niches." (PMID 39859345, 2025). "Most notably, Notch 1 is a target of miR‐449a, through which circRNA‐000911 influences breast cancer progression." (PMID 40761890, 2025). "For instance, SNHG7 was described as an EMT-promoter in breast cancer cells, where it sponged miR-34a, leading to the activation of the Notch-1 pathway." (PMID 38948025, 2024). "Notch 1–4 receptors have intricate and context-dependent roles in the development and progression of breast cancer." (PMID 37726449, 2024). "Simultaneous expression of Notch-1 and Jagged-1 in breast cancer is thought to stimulate self-renewal of the tumor-initiating population, and in head and neck carcinomas to facilitate tumor progression through cell proliferation." (PMID 38314334, 2024). "High levels of Notch-1/2/3/4 have been identified in breast cancer, where Notch-2 is considered as a tumor suppressor, and in cervical cancer in correlation with a poor overall survival." (PMID 38314334, 2024).
breast cancer (continued). "These include EMT (TWIST1, SNAIL1, RUNX1, RUNX2, HIF1, and NOTCH1), breast cancer maintenance (OCT4, SP1, GATA1, ATF1, FOXO3a, ELK1, VDR, and NRF1), pro-metastatic responses (SMAD2/3, HNF1a, GLI1, NANOG, YY1, MYB1, and AP1), and immune modulation (STAT1/3)." (PMID 38398186, 2024). "The upregulation of NRF2 stimulates the expression of G6PD and activates HIF-1α, resulting in NOTCH1 signaling activation and breast cancer proliferation." (PMID 38424190, 2024). "PF also inhibited the proliferation and invasion of breast cancer cells in the Notch-1 signaling pathway by interfering with breast cancer MDA-MB-231 and MCF-7 cells." (PMID 38611704, 2024). "CCL20-modulated PMN-MDSCs secreted amounts of CXCL2 and activated NOTCH1/HEY1 signaling pathway in breast cancer cells by binding to CXCR2, leading to the increase of ALDH+ BCSCs." (PMID 36859354, 2023). "Correspondingly, blockade of Dll4 binding to Notch1 significantly decreased tumor growth and vasculature of mouse mammary tumors already resistant to VEGF blockade." (PMID 38269089, 2023). "Notch1 knockdown in breast cancer cells suppressed the EMT process, tumour growth, migration, and invasion using in vitro and in vivo models." (PMID 37627137, 2023). "IHC in breast cancer patient samples revealed the upregulation of NICD1 and Jag2 in the invasive front rather than within the core of the tumor, suggesting Jag2 mediated Notch1 activation playing a role in breast cancer invasion and metastasis." (PMID 38269089, 2023). "Using live imaging of an NF-κB activity reporter and staining of fixed tissues from mouse and human breast cancer, we further determined that for maximal induction of MenaINV in cancer cells, NF-κB needs to cooperate with the Notch1 signaling pathway." (PMID 37024946, 2023). "The effect of lncRNAs on the chromatin organisation affecting the Notch1 pathway has also begun to be elucidated in breast cancer (MDA-MB-231) cells." (PMID 37628760, 2023). "Notch 1 and 4 inhibition impair breast cancer stem cell activity by reducing ALDH activity thus reducing tumor growth and render CSCs resistant to drug therapy." (PMID 37492224, 2023). "Notch1 inhibition increases sensitivity to paclitaxel in a breast cancer model by affecting the pool of CSC through miR-34a upregulation." (PMID 37568775, 2023). "The visfatin-neurogenic locus notch homolog protein 1 (Notch-1) pathway contributes to breast cancer development by activating NF-κB signaling, while high circulating visfatin levels reportedly significantly increase the risk of cancer." (PMID 37286356, 2023). "In summary, we have found that macrophages enhance expression of MenaINV, a pro-metastatic isoform of Mena, in breast cancer cells through Notch1-mediated prolongation of NF-κB activation." (PMID 37024946, 2023). "We have previously found that MenaINV mRNA and protein expression are upregulated in breast cancer cells upon their direct cell contact with macrophages through Notch1 signaling." (PMID 37024946, 2023). "Notch 1 and Notch 4 are enriched in BCSCs compared to differentiated cells, both receptors have been reported to regulate breast cancer stem cells." (PMID 37492224, 2023). "HER2+ breast cancer cells can activate ERK signaling which decreases Notch1 cleavage, thus stabilizing survivin to promote HER2+ cell survival." (PMID 37440925, 2023). "Np9 was shown to not only activate MAPK, AKT, and NOTCH1 signaling pathways (see Results HERVs in Breast Cancer—The Rise of New Biomarkers), but also to upregulate β-catenin, which is (HGNC: CTNNB1) essential for survival of leukemia stem cells." (PMID 36979914, 2023). "In breast cancer, elevated NOTCH1 expression is significantly associated with poor-prognosis breast cancer, while NOTCH2 expression is associated with good-prognosis breast cancer." (PMID 37686600, 2023). "It has been proven that Notch1, and its ligand, Jagged 1, are expressed in human breast cancer, particularly in basal-like mesenchymal stem-like TNBC subtypes." (PMID 37296801, 2023).
breast cancer (continued). "The coactivation of STAT3 and NOTCH1 is associated with cisplatin resistance in HNSCC, and the simultaneous downregulation of STAT3 and NOTCH1 using siRNA enhances chemosensitivity in breast cancer." (PMID 37373457, 2023). "Analyses in breast cancer patients revealed a positive correlation between breast cancer recurrence and the expression levels of Notch1 and its ligand Jagged1." (PMID 37440925, 2023). "Taken together, we confirmed that CXCL2-CXCR2 axis, which was activated by CCL20-modulated PMN-MDSCs, enhanced the stemness of breast cancer cells by NOTCH1/HEY1 signaling pathway." (PMID 36859354, 2023). "Further, higher Notch1 and CD73 expression associated with poor overall survival in a set of 1247 breast cancer patients." (PMID 37391408, 2023). "Evidence suggests, activation of Notch1 causes suppression of E-cadherin, which leads to EMT occurrence in breast cancer cells." (PMID 36429127, 2022). "USP8 promotes the progression of breast cancer via deubiquitinating and stabilizing Connexin-43 (Cx43) and Notch1 intracellular domain (NICD)." (PMID 35361778, 2022). "One potential mechanism is the activation of NF-kB signaling by NOTCH-1, resulting in invasive growth and migration of breast cancer cells." (PMID 36476410, 2022). "Here, we report that NOTCH1 activity is indeed involved in cell proliferation and drug resistance in breast cancers, both estrogen-depended and TNBC." (PMID 35585598, 2022). "G6PD acts as an oncogene in many types of cancers and Nrf2 promotes breast cancer cell migration via up-regulation of G6PD/HIF-1α/Notch1 axis." (PMID 35818395, 2022). "Recently, it was demonstrated that Notch1 also mediated the Nrf2-induced regulation of breast cancer." (PMID 36818671, 2022). "NOTCH1, NOTCH3, and JAG1 expression are associated with poor survival in breast cancer patients, and NOTCH overexpression transformed MCF10A breast cells whilst overexpression of NUMB reversed this transformation." (PMID 36012147, 2022). "In breast cancer cell lines, Notch-1 signaling induced by doxorubicin promoted ABCC1 overexpression." (PMID 35163586, 2022). "NOTCH1 plays a key role in breast cancer progression by increasing proliferation, maintenance of cancer stem cells, and impairment of cell death." (PMID 35585598, 2022). "Breast cancer HER2+ cells with acquired resistance to an anti-HER2 therapy showed overexpression of Notch-1 and its canonical target genes." (PMID 36383805, 2022). "For example, it has been shown that NOTCH-1 high-expressing women with breast cancer had a 66% mortality rate compared to 30.5% for patients with low expression levels." (PMID 36476410, 2022). "The inhibition of ubiquitin-specific protease 8 (USP8), a novel deubiquitylase of the Notch1 intracellular domain, downregulated the Notch signal pathway, resulting in the retardation of cell growth and colony forming ability of breast cancer cell lines." (PMID 36553667, 2022). "Notch2 overexpression predicts better overall survival in women with breast cancer, which is completely different from Notch1." (PMID 36139447, 2022). "Notch1 signaling affected the development of breast cancer cells by affecting its downstream genes HES-1 and p21." (PMID 36289931, 2022). "Concomitant hyperactivation of the Notch1 pathway, involved in breast cancer progenitor cell maintenance, and the ERK pathway has been found more frequently in TNBC." (PMID 36358725, 2022). "In breast cancer cells, it was shown that the overexpression of Nrf2 augments the expression of Notch1 via G6PD/HIF-1α pathway." (PMID 35417854, 2022). "In breast cancer cells, the suppression of Notch-1 by genistein coincides with the downregulation of cyclin B1 and Bcl-2, and this effect is mimicked by Notch-1 siRNA treatment." (PMID 35408894, 2022). "High levels of JAG1, JAG2, and NOTCH1 as well as DLL4 expression were detected and linked to poor survival or nodal and distant metastasis in human breast cancer." (PMID 36017236, 2022).